AR (androgen receptor)
Diseases named in the same sentence as AR in open-access papers (continued):
Sharing a sentence is not in itself a finding about the gene and the disease.
prostate carcinoma (continued). "In prostate cancer cells, SIRT7 undergoes upregulation to inhibit SMAD4, leading to activation of AR signaling, subsequent induction of autophagy and enhancing cancer progression." (PMID 35317831, 2022). "Correspondingly, AR inhibition or AR antagonist treatment can restore ARHGEF2 expression, thereby allowing prostate cancer cells to induce treatment resistance and tolerance." (PMID 36335093, 2022). "Studies have found that prostate cancer has abnormally high levels of MAGEA11 and high androgen receptor protein expression, and increased MAGEA11 expression is directly related to the progression of prostate cancer." (PMID 36292195, 2022). "It was recently found to inhibit the transcriptional activities of the full-length AR and AR-v7 protein (0.3 μM for 24 h) via a HDAC-related mechanism in prostate cancer 22RV1 cells." (PMID 35372068, 2022). "Initially, it is androgen-dependent, but it eventually develops into castration-resistant prostate cancer (CRPC), which is incurable with current androgen receptor signaling target therapy and chemotherapy." (PMID 35892678, 2022). "Potent androgen receptor (AR) pathway inhibitors (ARPIs), such as enzalutamide (ENZ) and abiraterone (Abi), have increased patient survival with advanced prostate cancer disease;1,2 however, resistance ultimately occurs." (PMID 35477723, 2022). "The dysregulation of androgen receptor (AR) and PI3K/Akt signaling cascades is related to the development of prostate cancer." (PMID 35280689, 2022). "More recently, G6PD levels have been found to be elevated in prostate cancer, with G6PD proposed as a mediator of AR signaling." (PMID 35213227, 2022). "AR activation has previously been shown to downregulate MYC in normal prostate epithelial cells and models of prostate cancer." (PMID 36194476, 2022). "These CREs were preferentially bound by other key prostate cancer transcription factors, including FOXA1 and the AR." (PMID 36212399, 2022). "Specifically, the AR and its isoforms were found to be positively correlated with MYC expression in primary prostate cancer and in CRPC." (PMID 36212399, 2022). "Treatment of prostate cancer cells with FK506, which binds to the FK1 domain of FKBPs, or with MJC13, an inhibitor of FKBP52–AR signaling, also inhibited AR dimer formation." (PMID 34057812, 2022). "In research on prostate cancer cells, senescence was induced either by androgen receptor antagonist—enzalutamide (ENZ)—or by androgen receptor agonists at supraphysiological androgen level (SAL)." (PMID 36232388, 2022). "Together, these data show that SWI/SNF ATPase inactivation specifically leads to genome-wide collapse of the AR, FOXA1, ERG and MYC-activated core enhancer circuitry in prostate cancer cells." (PMID 34937944, 2022). "In prostate cancer, USP22 predicts disease outcome and promotes the CRPC phenotype by controlling AR and MYC dual regulation." (PMID 35935969, 2022). "Alternative splicing in AR and gene fusion events for TMPRSS2 with ETS-family members are involved in prostate cancer." (PMID 35328625, 2022). "Its significance for signal transduction, cell death, and androgen receptor (AR) expression was studied in PC-3, LnCaP, and DU-145 human and TRAMP-C2 murine prostate cancer cells." (PMID 35453310, 2022). "Further study revealed that the expression of the glucocorticoid receptor (GR) gene was depressed by AR and TLE3 in prostate cancer cells." (PMID 36438567, 2022). "On the other hand, DL3, an antagonist for AR signaling, was reported to downregulate HSP72 expression by reducing mRNA transcription with marginal effects on mRNA stability in human prostate cancer cells." (PMID 35805135, 2022).
prostate carcinoma (continued). "In this study, we also identified the significant correlation in co-occurrence of altered AR, IGF1R, and Wnt/β-catenin signaling pathways in both primary and advanced human prostate cancer samples." (PMID 35902588, 2022). "Androgen receptor (AR) is an important prognostic marker and therapeutic target in luminal androgen receptor triple-negative breast cancer (LAR TNBC) and prostate cancer (PCa)." (PMID 35013318, 2022). "In human prostate cancer, HIF-1 signaling has been shown to limit AR gene expression and thus lead to resistance to AR antagonist drug therapy." (PMID 36288137, 2022). "As prostate cancer is an androgen-dependent tumor, androgen deprivation therapy (ADT) and inhibition of the androgen receptor signaling pathway are the main endocrinologic treatments for patients with metastatic prostate cancer." (PMID 37113653, 2022). "In prostate cancer, PA2G4 was found to downregulate the expression of androgen receptor (AR) and AR-regulated genes, leading to lower incidence and weight of LNcaP tumors." (PMID 35526051, 2022). "We found a significant inverse correlation between TNF and AR activity in human patients, validating our finding that TNF signaling is induced in prostate cancer upon castration." (PMID 36511483, 2022). "To evaluate the therapeutic efficacy of the Au‐AR pep‐PROTAC drug in vivo, we established two subcutaneous xenograft mouse models of prostate cancer with C4‐2 cells (5 × 106, AR‐positive) and CWR22rv1 cells (5 × 106, AR&AR‐V7‐positive)." (PMID 35971165, 2022). "Strikingly, treatment with enzalutamide, an effective AR inhibitor, reduces NSUN2 expression and decreases the m5C modification level in prostate cancer cells." (PMID 36169095, 2022). "This work identifies high AR activity as a predictive biomarker of response to BAT and supports a treatment paradigm for prostate cancer involving alternating between AR inhibition and activation." (PMID 36194476, 2022). "In prostate cancer cells, HOXB13 interacts with the androgen receptor (AR) to modulate its transcriptional output." (PMID 35104804, 2022). "TMPRSS2 has been intensively studied in prostate cancer as it is an AR-up-regulated gene, which occurs as a gene fusion of its promoter with ETS family transcription factors in over two-thirds of prostate cancer patients." (PMID 35328625, 2022). "In promoting proliferation in ART, CREB5 exhibited a strong degree of interaction with known AR transcription machinery, including FOXA1, HOXB13, and GRHL2, as well as novel prostate cancer regulators TBX3 and NFIC." (PMID 35550030, 2022). "Activation of AR stimulates the phosphorylation of CREB (Ser133) in a PKC-dependent manner in hippocampal neurons and in an ERK-dependent manner in prostate cancer cells and Sertoli cells." (PMID 36272644, 2022). "Other groups also found a co-localization area of AR and NE markers, especially SYP in hormone-treated prostate cancer samples." (PMID 36033483, 2022). "One well-known factor affecting HSPs is the androgen receptor (AR)—a main player involved in the development of BPH and the progression of prostate cancer." (PMID 35055079, 2022). "Localized prostate cancer (PC) is curable, but options are limited for recurrent or metastatic tumors developing resistance to androgen-deprivation therapy (ADT) or AR targeted therapy (ART), known as metastatic castration-resistant prostate cancer (mCRPC)." (PMID 36323882, 2022). "Brg1 was previously reported to reside on the proximal promoter region of AR and to activate AR and PSA in prostate cancer;33,34 in our study, we found that Brg1 indeed transcriptionally regulated AR expression through qPCR and ChIP-qPCR assays." (PMID 35233061, 2022). "Here, we provide an overview of AR-dependent molecular mechanisms which drive CRPC and their potential crosstalk with ECM stiffening in promoting castrate-resistant growth of prostate cancer." (PMID 35740556, 2022).
prostate carcinoma (continued). "Taking prostate cancers as an example, while AR-independent prostate cancer cells are sensitive to CAP-induced ROS elevation, antioxidant treatment is feasible in AR-positive or castration-resistant prostate cancers." (PMID 36551308, 2022). "A decrease in miR-215 levels is correlated with an increase in KDM1B levels in enzalutamide-resistant prostate cancer cells that promotes AR-dependent AGR2 transcription and regulates the sensitivity to AR-targeted therapy." (PMID 36467881, 2022). "To elucidate the regulatory mechanism of AR by FKBP51 and FKBP52, we examined the expression of FKBP51 and FKBP52 in normal cells as well as multiple prostate cancer and bladder cancer cell lines." (PMID 34057812, 2022). "The upregulation of NSD2 expression acts as a key function for prostate cancer cell proliferation, survival, and tumor angiogenesis, and ATAD2 acts as an AR co-activator that enhances its transcriptional activity." (PMID 36008934, 2022). "Inspired by the findings that the AR signaling pathway is one of the most deregulated pathways by the G3BP1-SPOP ubiquitin signaling axis, we set to investigate its potential role in prostate cancer pathogenesis." (PMID 35252555, 2022). "Data from prostate cancer cell lines and patient tissues revealed that YAP and AR form a protein complex that primarily occurs in the cell nucleus." (PMID 35740556, 2022). "In breast and prostate cancer, EZH2 drives transcriptional activation by interacting with NF-κB and the androgen receptor, respectively, and recent findings suggest that EZH2-cMYC complexes co-activate joint gene signatures, thus promoting acute leukemia." (PMID 35884510, 2022). "Metastatic prostate cancer is treated Androgen deprivation therapy (ADT), Androgen receptor inhibitors (ARIs), chemotherapy and radiation therapy." (PMID 35447901, 2022). "In prostate cancer cells, HSP90 positively regulates AR stability and activity, and its inhibition will induce androgen receptor degradation." (PMID 35055079, 2022). "Altogether, owing to its role in pioneering, or unpacking the chromatin, for the AR, FOXA1 poses as a key prostate cancer-specific regulator of disease progression and therapeutic response." (PMID 36212399, 2022). "Abnormal AR signaling contributes to different human diseases, such as androgen insensitivity syndrome (AIS) and prostate cancer." (PMID 35053220, 2022). "Although RM1 cells do express AR, others have shown that RM1 are insensitive to androgen deprivation in vitro and in vivo, thus representing aggressive prostate cancer." (PMID 35604506, 2022). "AR pathway activation also leads to SIRT3 transcriptional repression, thus enhancing mitochondrial aconitase activity and driving prostate cancer malignancy and bone invasion." (PMID 35328633, 2022). "Although AR and MYC are both central to prostate cancer etiology, our current understanding of the interplay between these two transcription factors is scarce." (PMID 35562350, 2022). "We report a new mechanism of androgen receptor (AR) mRNA regulation and cytoprotection in response to AR pathway inhibition (ARPI) stress in prostate cancer (PCA)." (PMID 34939643, 2022). "Analyses of clinical specimens reveal that concurrent low AR and high MYC transcriptional programs accelerate prostate cancer progression toward a metastatic, castration-resistant disease." (PMID 35562350, 2022). "Once prostate cancer progresses to become castration-resistant prostate cancer (CRPC), therapy is based on androgen receptor inhibition and/or antimitotic taxane chemotherapy which improve survival in patients." (PMID 36325358, 2022). "It works as a powerful AR antagonist and a selective CYP17 inhibitor, inducing an increase in AR protein breakdown and lowering AR expression in prostate cancer cells." (PMID 36551557, 2022).
prostate carcinoma (continued). "By downregulating AR expression, MIR381 suppresses proliferation and progression of prostate cancer cells." (PMID 35317831, 2022). "It was found that quercetin was able to reverse drug resistance in paclitaxel-resistant prostate cancer cells in vitro by reversing the activation of the androgen receptor and PI3K/Akt signaling pathway in prostate cancer treatment." (PMID 35684449, 2022). "The ameliorative effect of SeNPs in prostate cancer was indicated by overexpression of necroptosis related to IRF1 and TNF, a decrease in expression of PSA and AR, and an increase in ROS-mediated necroptosis in PC-3 cells." (PMID 36290639, 2022). "Androgen receptor activates CREB3L2, increasing protein trafficking in prostate cancers, but the biochemical details remain to be elucidated." (PMID 36313580, 2022). "Briefly, AR signaling plays a key role in prostate cancer development and progression, and androgen deprivation therapy (ADT) is used to suppress prostate cancer progression." (PMID 35236381, 2022). "The LNCaP cell line, isolated from a subclavian lymph node metastasis of prostate cancer, maintains several key markers including prostate-specific antigen (PSA), prostate specific membrane antigen (PSMA) and the androgen receptor (AR)." (PMID 35164354, 2022). "Fortunately, with the group of androgen receptor (AR) inhibitors such as apalutamide and enzalutamide, the updated guidelines provide us another highly effective class of which are approved in metastatic hormone sensitive prostate cancer irrespective of risk factors." (PMID 36292031, 2022). "In prostate cancer, MUC1-C inhibits androgen receptor (AR) axis signaling and induces the expression of the neural BRN2 transcription factor, increasing the self-renewal capacity and tumorigenicity of prostate cancer cells." (PMID 35879749, 2022). "They show that ETS-related gene (ERG), which has been well established in diverse human cancers, through its physical interaction with AR in prostate cancer LNCaP-LnTE3 cells using PLA, induces AR aggregation and endoplasmic reticulum stress." (PMID 37435453, 2022). "The discovery of induced synthetic lethality using co-inhibition of AR and PARP has opened the doors for investigation of this combination approach as a new treatment option for advanced prostate cancer." (PMID 35159068, 2022). "The combination of AR inhibition by enzalutamide (AR antagonist) and AZD7762 (CHK1/2 inhibitor) showed a synergistic effect in xenograft models of prostate cancer." (PMID 35163621, 2022). "Given that prostate cancer cell growth is coupled to AR signaling, which in CRPC is linked to de novo steroidogenesis that uses cholesterol as a precursor, we hypothesized that LDL-inducible changes in cell proliferation of AR-positive C4-2B cells could be associated with activation of AR signaling." (PMID 35033184, 2022). "It has also been demonstrated that AR and the gene expression of UPR are correlated in prostate cancer." (PMID 36359245, 2022). "As a co-activator for the androgen receptor (AR), SRCAP promotes the proliferation and mediates the expression of prostate-specific antigen in prostate cancer." (PMID 35152838, 2022). "Belinostat (PXD101) suppressed Hsp90 activity, GSK-3β, and AR function by HDAC6 inhibition and prevented the development of castration-resistant phenotype in prostate cancer cells." (PMID 35582529, 2022). "First, we asked if KCZ or KCZ-7 inhibited tGLI1-positive breast cancer through androgen receptor antagonism, since KCZ is known to inhibit the androgen receptor and has shown clinical efficacy as a second-line therapy for castration-resistant prostate cancer." (PMID 36077791, 2022).
prostate carcinoma (continued). "Therefore, AR may play biphasic roles in different stages of neuroendocrine differentiation in prostate cancer, and the molecular characteristic of AR during the progression of neuroendocrine differentiation would potentially guide the clinical therapeutic strategy and future investigations." (PMID 36033483, 2022). "The clusters isolated from the first patient expressed AR, KLK3 (PSA), or FOLH1(PSMA), displaying a profile similar to androgen-responsive LNCaP cells sequenced as one of the positive controls for prostate cancer cells." (PMID 35697674, 2022). "Similar to that observed in the 22Rv1 prostate cancer cells, treatment with 5 nM of DHT, a natural ligand of AR, significantly increased the expression levels of AR protein in Hs578T and SUM159PT TNBC cells." (PMID 35960413, 2022). "Global transcriptomic profiling with RNA sequencing (RNA-seq) revealed significant downregulation of AR and FOXA1-regulated genes in multiple prostate cancer cells, as well as ERG-regulated transcripts in ERG fusion-positive VCaP cells." (PMID 34937944, 2022). "Androgen receptor (AR) pathway inhibition (ARPI) induces profound and sustained responses in advanced prostate cancer (PCA)." (PMID 34939643, 2022). "In prostate cancer, it was observed that STAT3 activation induces stem cell-like phenotypes due to regression of androgen receptor expression." (PMID 36359888, 2022). "Results of the present study further extended the current knowledge of the TPX2/AR pathway and uncovered the potential of TPX2 in the treatment of prostate cancer." (PMID 35444697, 2022). "Consistent with the degradation of the AR protein, PROTAC 16 inhibited AR-mediated gene expression and proliferation of androgen-dependent prostate cancer cells." (PMID 35702041, 2022). "Another recent study has found that the well-characterized antitumor agent SBF-1 can selectively bind to the AR-DBD and block the transcription of AR target genes, and has been proven to repress prostate cancer growth both in vitro and in vivo." (PMID 35864113, 2022). "Similarly, it was also demonstrated that SIRT1 deacetylates AR and histone H3 at the promoter region of the prostate-specific antigen gene to suppress AR-mediated gene transcription, thereby inhibiting the proliferation of androgen-responsive LNCaP prostate cancer cells." (PMID 36291902, 2022). "TMPRSS2-ERG rearrangement, the most common ETS gene fusion in prostate cancer, brings ERG expression under androgen control via androgen receptor-mediated TMPRSS2 regulation and results in over-expression of ERG protein." (PMID 35513774, 2022). "Because of this direct regulation by AR, CAMKK2’s functions in prostate cancer were largely assumed to be limited to classic, AR+ adenocarcinomas." (PMID 35741020, 2022). "De novo NEPC accounts for <2% of all prostate cancer at the time of diagnosis, but the incidence of NEPC has significantly increased with the clinical application of AR inhibitors." (PMID 35864113, 2022). "Additionally, compounds targeting the NTD or the DBD domains of AR have received attention, as they may affect constitutively active AR splice variants (ARVs), which lack the entire LBD and are involved in castrate resistant prostate cancer (CRPC)." (PMID 36139361, 2022). "Altogether, the results provide further evidence of opposing functions for the AR and MYC in prostate cancer, as well as the role that chromatin remodeling plays in this dynamic." (PMID 36212399, 2022).